DCN (decorin)
Diseases named in the same sentence as DCN in open-access papers (continued):
Sharing a sentence is not in itself a finding about the gene and the disease.
tumor (continued). "In theory, gene delivery of specific ECM macromolecules such as collagen and decorin could also be applied to encapsulate the tumour mass, thus possibly restricting tumour growth and metastasis." (PMID 26056582, 2014). "This raises the question whether differential decorin expression in different tumor samples may have clinical, prognostic significance." (PMID 24634138, 2014). "Decorin, mimecan, hemoglobin subunit alpha, hemoglobin subunit beta, and keratin type I cytoskeletal 19 were upregulated in normal tissue, whereas periostin and versican core protein were upregulated in phyllodes tumor tissue." (PMID 25400079, 2014). "We thus propose decorin as a new therapeutic target for these aggressive tumours." (PMID 24142880, 2013). "Downregulation of TGF-β production by decorin could also facilitate anti-tumor immune responses through inhibition of immuno-suppressive T cells." (PMID 23898462, 2013). "In addition, several genes related to cell migration, adhesion to substrate and regulation of ECM organization were also co-regulated with DCN, suggesting another link of decorin with tumour cell migration or invasion." (PMID 24142880, 2013). "As decorin acts as a natural antagonist for IGF-IR in tumours, its decreased expression may contribute to increased IGF-IR activity, thus leading to the progression of IGF-IR-dependent cancers through enhanced cellular motility and invasion." (PMID 24146840, 2013). "In addition, decorin is also involved in various pathological processes, such as wound healing, fibrosis, inflammation and tumor invasion, in which remodeling of connective tissues occur." (PMID 24023624, 2013). "Oversecretion of proteolytic enzymes by MB49-I was observed, and could promote tumour invasiveness, but we asked here whether the immune system and other secreted factors including decorin could also play a role in increased in vivo growth of MB49-I." (PMID 24142880, 2013). "In addition, we also demonstrated a role for decorin in promoting invasiveness into matrigel of the mouse tumour cell line in vitro." (PMID 24142880, 2013). "Decorin has also been shown to inhibit tumor growth by antagonizing tumor angiogenesis." (PMID 23007289, 2013). "Since decorin has been shown to promote tube formation from endothelial cells and inflammation-induced angiogenesis, we next asked whether decorin plays a role in angiogenesis in our tumour model." (PMID 24142880, 2013). "Thus, these in vivo data provides further proof that decorin significantly affects the tumor microenvironment via induction of Peg3, Bmp2k and Zc3hav1 at the protein and transcriptional levels as suggested by the mixed microarray data." (PMID 23029096, 2012). "We hypothesized that establishment of a co-culture approach could reconstitute in part the decorin-evoked in vivo stromal gene expression signatures obtained from the tumor xenografts in an in vitro setting." (PMID 23029096, 2012). "Kaplan-Meier analysis (median follow-up of 12.8 years, range: 1.1 to 23.5 years) showed that patients whose tumours express high levels of DCN or HSP90B1 in the malignant epithelium have significantly lower OS and DFS compared to patients with lower expression of either marker." (PMID 22363530, 2012). "In addition to in vitro studies, decorin has also been reported to inhibit angiogenesis in tumor xenograft in vivo in nude mice." (PMID 22039486, 2011). "Interestingly, there was a marked stromal decorin and versican accumulation surrounding intraductal epithelial proliferations and in situ tumor components." (PMID 21791066, 2011). "Given the importance of IL-8 in tumor migration and invasion, we tested whether IL-8 was involved in nuclear decorin silencing mediated migration and invasion suppression in our system." (PMID 21958730, 2011).
tumor (continued). "This might be due to sequestration of decorin in the nucleus and consequent inability to interact with membrane receptors to which extracellular decorin is known to bind to effect tumor growth in other cancers." (PMID 21958730, 2011). "The protein product of DCN (decorin) is capable of suppressing the growth of various tumor cells." (PMID 21799901, 2011). "Our observations appear to be consistent with the very interesting emerging evidence of a broader role of PDGFRs in tumor stromogenesis, and with the increasing interest in the role of decorin and lumican via the tyrosine kinase receptor family in cancer biology." (PMID 20421977, 2010). "The tumour suppressor activity of decorin is mediated through various pathways." (PMID 19678923, 2009). "Decorin expressing tumours suppress neovascularization by inhibiting vascular endothelial growth factor (VEGF) mRNA expression which leads us to suggest that decorin may be induced during plexiogenesis." (PMID 16390543, 2006). "Kaplan–Meier analyses showed that neither the fraction nor the intensity of DCN in tumour cells was prognostic, that a high intensity of DCN in the stroma was associated with a longer OS (p = 0.048), and that the intensity of DCN in immune‐rich areas was not prognostic." (PMID 41392017, 2026). "In addition, the animal model treated with decorin showed delayed tumor development." (PMID 41210271, 2025). "Moreover, we also found that combining decorin and GM-CSF could slightly enhance the anti-tumor effects in CT26 model." (PMID 39306655, 2024). "This suggests that the increased rates of recurrence and reduced survival observed in STS with high VEGF and low decorin levels in the current study could be due to a wider distribution of satellite cells radiating beyond the immediate circumference of the tumour." (PMID 37104411, 2023). "However, at a physiological level, decorin is recognised as an important tumour suppressor." (PMID 37104421, 2023). "iCAF and decorin are related to poor prognosis, and, by imaging mass cytometry, poor responders present high collagen expression, which may represent a barrier between T cells and tumor cells." (PMID 37563240, 2023). "Additionally, our data showed that PGM5-AS1 could target miR-4284 to enhance DCN expression in CC cells, thereby suggesting that PGM5-AS1 acts as an anti-tumor lncRNA in CC by targeting the miR-4284/DCN axis." (PMID 35420507, 2022). "Immunohistochemical co-staining DCN and integrin β1 in the same clinical tissue shows that DCN dynamically regulated the protein expression of integrin β1 in terms of a decrease in DCN accompanied by integrin β1 upregulation from normal, to primary tumor, to PVTT tissues." (PMID 34504839, 2021). "The plasma level of DCN was negatively correlated with stromal DCN expression only in patients with advanced disease, indicating that the plasma level of DCN increased as a consequence of the cancer progression via unknown tumor-derived factors." (PMID 34884232, 2021). "In conclusion, decorin may effectively inhibit metastatic tumor formation in the liver." (PMID 32824864, 2020). "Thus, decorin may suppress the proliferation of HCC through direct and indirect tumor inhibitory effects and may be associated with prognosis in patients with HCC." (PMID 32231160, 2020). "Moreover, Decorin suppressed tumor cell invasion through IGF-IR inhibition." (PMID 32795296, 2020). "In tumor tissues, the decreased expression of decorin may related to methylated DCN gene." (PMID 32477937, 2020). "To fill up this hiatus we hypothesized that decorin may act as a tumor suppressor in HCC." (PMID 32477937, 2020).
tumor (continued). "Furthermore, noteworthy is the idea of “normalization of the tumour microenvironment” whereby decorin in its part could orchestrate cancer cells towards a less malignant phenotype, and maybe even to a less malignant behaviour." (PMID 28653173, 2017). "Together, these results demonstrated that co-expression of IL-12 and DCN by a single oncolytic Ad vector induced a potent antitumor effects by inducing extensive necrosis, efficient infiltration of immune cells, and proficient viral distribution in tumor tissues." (PMID 28002796, 2017). "For example, DCN inhibits neural stem/progenitor cell differentiation into neurons and supports axonal regeneration through interaction with cell adhesion molecules and growth factors in the central nervous system, although its role in the proliferation of tumor cells is controversial." (PMID 28814279, 2017). "Thus, in theory, a single DCN molecule could simultaneously sequester multiple important mediators of tumor growth and antagonize multiple signaling pathways crucial for tumor growth and progression." (PMID 26697491, 2015). "We demonstrated that treatment strategies containing metformin significantly reduced tumor growth and metastasis in nude mice, and that metformin caused an increase in AMPK and PTEN activity and suppression of mTOR/p70S6K/S6, as well as invasion/migration-associated genes, e.g., MMP7, DCN and FN1." (PMID 25909163, 2015). "Therefore, decorin is now being reconsidered as a novel and native signaling ligand rather than a structural protein alone, that contributes to numerous pathophysiological processes, including inhibition of tumor growth, metastasis, and angiogenesis." (PMID 26379028, 2015). "Furthermore, it is known that decorin antagonizes the angiogenic network due to the inhibition of the production of VEGF (vascular endothelial growth factor) by tumor cells and can directly blocking of VEGFR2 (vascular endothelial growth factor receptor-2) at the same time." (PMID 26248280, 2015). "Downregulation of decorin in the tumor stroma may facilitate tumor invasion to neighboring tissues." (PMID 24634138, 2014). "Of the five clinical variables available (histologic grade, ER-status, PgR-status, age, lymph node-status and tumor size) after backward elimination only lymph node-status and tumor size remained significant in the multivariate Cox models with proliferation and stromal-decorin or stromal-laminin." (PMID 22719844, 2012). "Further, our top gene ontology classes strongly suggests an unexpected and preferential role for decorin protein core to inhibit genes necessary for immunomodulatory responses while simultaneously inducing expression of those possessing cellular adhesion and tumor suppressive gene properties." (PMID 23029096, 2012). "Decorin has also been implicated in the modulation of both postnatal mammary stromal cell phenotypes and MEC behaviour in tumours, suggesting that Decorin may play a regulatory role in mediating mammary tissue interactions from early developmental stages onward." (PMID 21834968, 2011). "Interestingly, although many tumour suppressor effects have been associated with decorin, no precise quantification by real time PCR has been performed." (PMID 19678923, 2009). "The panel allowed for identification of DCN, CD4+ T cells, CD8+ T cells, CD20+ B cells, CD68+ macrophages, and PanCK+ tumour cells." (PMID 41392017, 2026). "In vivo experiments further confirmed that OAV-Decorin can promote IFN-γ expression, suppress TGF-β expression, improve the tumor-suppressive microenvironment, and ultimately achieve an antitumor effect." (PMID 41924602, 2026). "Decorin also destabilizes E‐cadherin via EGFR/ERK signaling, suppressing tumor cell invasion and metastasis." (PMID 40542654, 2025).
tumor (continued). "All PDGCAs expressed markers of tumor epithelial and stem cells (EPCAM, CDH1, KRT18, CA9, CD24, CD133), stromal and extracellular matrix components (COL3A1, COL5A1, DCN, PDGFRA, and PDGFRB), and mesenchymal stem cells (CD73, CD105, CD90)." (PMID 40723172, 2025). "The downregulation of decorin in mammary fibroblasts was shown to activate the IL-6/STAT3/AUF1 axis, converting normal fibroblasts into tumour-promoting CAFs." (PMID 41463344, 2025). "In OSCC, the expression of DCN is reduced, which can impact OSCC angiogenesis, and inhibit tumor cell proliferation, migration, and invasion capabilities, serving as a potential marker for predicting adverse prognosis in OSCC patients." (PMID 40109852, 2025). "Among the 7 HRGs included in the hypoxia risk score model constructed in this study, these 6 genes (LDHA, PGK1, PFKP, DCN, LOX, FBP1) have been extensively reported in previous studies for their roles in tumor hypoxia response and progression." (PMID 40464853, 2025). "The qPCR results indicated that the expression of protective genes (DCN and CARHSP1) gradually decreased in para-tumor, tumor, and pvtt tissues." (PMID 40051627, 2025). "Decreased expression of DCN in OSCC can impact angiogenesis, and inhibit tumor cell proliferation, migration, and invasion, making it a potential marker for predicting poor prognosis in OSCC patients." (PMID 40109852, 2025). "The WB results showed that the expression of protective genes (DCN and CARHSP1) gradually decreased in para-tumor, tumor, and pvtt tissues." (PMID 40051627, 2025). "The combination of αPD-L1 and RdB/IL12/GMCSF, RdB/IL12/shVEGF, RdB/IL12/DCN, RdB/IL12/GMCSF-TK, or RdB/IL12/GMCSF-RLX also resulted in 66.7%, 83.3%, 50.0%, 50.0%, and 83.3% tumor regression on day 50 post initial treatment, respectively." (PMID 40335925, 2025). "Decorin can target multiple tyrosine kinase receptors, such as c-met, EGFR, and IGFR, which play important roles to support tumor growth and promoting tumor metastasis." (PMID 39306655, 2024). "This includes tumor growth-inhibiting as well as -activating signals, such as the potential regulation of the ETV4 transcriptional activity by DCN or the PLAU-PLAUR ligand-receptor interaction." (PMID 38200223, 2024). "Our results encompass a range of novel and well-known tumor growth-inhibiting as well as -activating signatures, such as the potential regulation of the ETV4 transcriptional activity by DCN or the PLAU-PLAUR ligand-receptor interaction." (PMID 38200223, 2024). "While LUM (lumican), DCN (decorin) and VASP (vasodilator stimulated phosphoprotein), that are known tumor suppressors were found to be downregulated in the EVs derived from NB patients." (PMID 38660306, 2024). "Previous studies have reported that decorin can effectively inhibit TGF-β signaling and enhance the therapeutic effect of oncolytic viruses on tumor metastasis." (PMID 39306655, 2024). "Both decorin, a natural inhibitor of TGF-β signaling, and CD40L, one of the strongest inducers of Th1 responses, are potential target for tumor therapy." (PMID 39306655, 2024). "This functional cluster of proteins was also identified by proteins involved in proteoglycan metabolism: in addition to lumican, decorin, and mimecan, UDP-glucose 6-dehydrogenase (UDP-GlcDH) was also identified, with the lowest level in the tumor." (PMID 39195201, 2024). "Studies in human neoplasms have revealed that both VEGF pathway components and decorin can change the microenvironment in a way that increases the development of neoplastic cell satellites in the surrounding tissue." (PMID 37104411, 2023). "The high purity of the fibroblast and tumor cell populations was confirmed by selective expression of cell type-specific genes including CDH1, EPCAM, and KRT8 for tumor cells and VIM, DCN, THY1, and COL3A1 for fibroblasts." (PMID 36868311, 2023).
tumor (continued). "YAP inhibitor administration attenuated the tumor suppressive effect of B.adolescentis-treated THP-1 cells and reduced the number of DCN+ macrophages in tumors on BALB/c nude mice." (PMID 37464382, 2023). "The abundance of B. adolescentis was correlated with the number of Decorin+ macrophages and the expression level of TLR2 in tumor tissue of CRC patients." (PMID 37464382, 2023). "To further investigate the clinical relevance, we quantified B.adolescentis and the expression of TLR2 and DCN with quantitative qRT-PCR analysis in paired fresh CRC and adjacent non-tumor tissue." (PMID 37464382, 2023). "Remarkably, hepatocyte areas adjacent to dHGP CRCLM showed upregulation of genes involved in tumor suppression and metastasis inhibition such as G0S2, ITIH2 and DCN." (PMID 36691028, 2023). "For example, decorin (DCN), a tumor suppressor gene (upregulated in RBPMS knockdown clones) affects the biology of various types of cancers by targeting a number of crucial signaling molecules involved in cell growth, survival, metastasis, and angiogenesis." (PMID 35008958, 2022). "We generated an engineered oncolytic adenovirus expressing decorin named OAV-Decorin (OAV-DEC), in the backbone of a tumor-selective oncolytic adenovirus ZD55 vector, in which E1B-55KD had been deleted." (PMID 34977339, 2022). "To conclude, we have shown that the combined use of OAV-Decorin and CAIX-CAR-T displayed synergistic antitumor effects in vitro and in vivo by enhancing T cell persistence, which led to prolonged survival of the tumor-bearing mice." (PMID 34977339, 2022). "The results showed that APOD, DCN, and PTN were downregulated in tumor samples compared with normal samples." (PMID 35420507, 2022). "Their results demonstrated that Decorin reduced collagen fibers and improved the spread of the viruses within tumor cells, and HRE-Ki67-Decorin had a higher ability to suppress tumor growth under hypoxic conditions than Ad-Decorin." (PMID 36424577, 2022). "Organoid cells were identified by the expression of the tumor markers KRT18 and KRT19 whereas CAFs were characterized by DCN and LUM expression." (PMID 36273171, 2022). "This novel signaling pathway of decorin/MET/mitostatin/Parkin transduces signals from high affinity decorin/MET interactions via an unidentified kinase or similar effector, for sustained tumor cell mitophagy." (PMID 35159071, 2022). "Our results showed insignificant upregulation of DCN and significant upregulation for miR-200c, MALAT1, lncTCF7 and ZFAS1 in metastases compared to the primary tumour." (PMID 35052821, 2022). "Overexpression of DCN in IBC cells markedly decreased migration, invasion, and cancer stem cells in vitro and inhibited tumor growth and metastasis in IBC xenograft mouse models." (PMID 33452400, 2021). "The ECM-related genes, DCN, COL11A1, LAMC3, and COL25A1, were also significantly downregulated in PVTT, compared with primary tumor tissues, indicating that the ECM is involved in macrovascular invasion by HCC." (PMID 34504839, 2021). "To validate the SWATH-MS data using an orthogonal approach, we performed immunohistochemical (IHC) analysis of tumour cell expression levels of two proteins, vinculin (VCL) and decorin (DCN), in our cohort." (PMID 33895336, 2021). "Involvement of TGFβ in the regulation of EMT phenotype, collagen synthesis and angiogenesis were assessed in aggressive tumor tissues with high ASPN expression and low DCN expression." (PMID 34379688, 2021). "To explore the downstream targets of DCN involved in inhibiting HCC metastasis, we analyzed proteins related to the epithelial mesenchymal transition (EMT) that are involved in tumor metastasis." (PMID 34504839, 2021). "Another example is decorin, small leucine-rich proteoglycans (SLRP) that control cell growth and migration in several tumor cell lines." (PMID 34976811, 2021).